PTPN2 (protein tyrosine phosphatase non-receptor type 2)
Diseases named in the same sentence as PTPN2 in open-access papers (continued):
Sharing a sentence is not in itself a finding about the gene and the disease.
breast cancer (30 papers, 2011 to 2024). A primary or metastatic malignant neoplasm involving the breast. "Specifically, PTPN2 is implicated in the subtype specificity of breast cancer, and low expression in patients with Luminal A and HER2-positive tumors is linked to a higher recurrence rate, but not in patients with triple-negative tumors." (PMID 35957898, 2022). "In one study, decreased expression of PTPN2 in ER+ breast cancer was associated with increased expression of nuclear p-AKT, resulting in an overall poorer response to tamoxifen treatment in breast cancer." (PMID 34884670, 2021). "Adoptive transfer of PTPN2‐deficient CD8+ T cells markedly repressed tumour formation in mice bearing mammary tumours." (PMID 31803974, 2020). "More importantly, PTPN2 expression deficiency has been shown to contribute to the rapid development and poor outcome in patients with breast cancer." (PMID 32285621, 2020). "Strikingly, we found that although PTPN2‐expressing central memory CD8+ HER‐2 CAR T cells modestly suppressed HER‐2‐E0771 mammary tumour growth, PTPN2‐deficient CD8+ HER‐2 CAR T cells eradicated tumours." (PMID 31803974, 2020). "In our studies, we found STAT‐5 and the resultant increased CXCR3 promoted the homing of PTPN2‐deficient CAR T cells to CXCL9/10‐expressing mammary tumours within 3 days of adoptive transfer." (PMID 31803974, 2020). "We have previously demonstrated a relation between PTPN2 and Akt in breast cancer, in low-risk breast cancer patients, PTPN2 protein loss was likewise associated with less pAkt in the cytoplasm and more in the nucleus." (PMID 31025094, 2019). "In summary, the results presented here confirm previous studies demonstrating low PTPN2 protein expression in half of the breast cancer cases and copy loss in 15–18% of the cases." (PMID 31025094, 2019). "This study aimed to evaluate PTPN2 protein expression in a large breast cancer patient material, its possible associations with PTPN2 loss, Akt activation, and the potential use as a new clinical marker in breast cancer." (PMID 30515568, 2019). "This is in line with previous findings in our lab, where 53.3% (354/664) low primarily cytoplasmic PTPN2 expression was found in a large cohort consisting of women with low-risk post-menopausal breast cancer." (PMID 31025094, 2019). "PTPN2 gene copy loss was reported in 16% and 18% in a high-risk post-menopausal breast cancer cohort and low risk, respectively." (PMID 31025094, 2019). "In this study, we aimed to evaluate PTPN2 protein expression in a large breast cancer cohort, its possible associations to PTPN2 gene copy loss, Akt activation, and the potential use as a clinical marker in breast cancer." (PMID 30515568, 2019). "Gene copy loss of PTPN2 and lower mRNA levels in breast cancer was associated with AKT activation and poor prognosis." (PMID 28322331, 2017). "Moreover, PTPN2 gene loss is associated with increased tumour cell growth and used as predictive markers of endocrine resistance in breast cancer." (PMID 32285621, 2020). "In this study, it was aimed to explore the role of PTPN2 loss in breast cancer." (PMID 31025094, 2019). "PTPN2 gene copy loss could be detected in 17.8% of the cases, which is in agreement with our previous study on a post-menopausal breast cancer cohort." (PMID 30515568, 2019). "Thus, PTPN2 may serve as a marker that predicts poor patient survival overall and poor response to antihormone treatment when it exhibits loss of function in breast cancer." (PMID 34884670, 2021). "Using OT-I TCR transgenic T cells and an ovalbumin (OVA)-expressing AT3 mammary tumour cell model, these investigators determined that Ptpn2−/− CD8+ T cell ACT enhanced tumour clearance compared to the control T cell ACT." (PMID 38334623, 2024). "Studies have shown that PTPN2 deletion is characteristic of acute lymphoblastic leukemia and breast cancer, suggesting that TCPTP functions as a tumor suppressor." (PMID 36670982, 2023).
breast cancer (continued). "PTPN2 has also been found to be a tumor suppressor in breast cancer and is frequently downregulated in multiple subtypes, including triple-negative breast cancer." (PMID 36968224, 2023). "Loss of PTPN2 enhances SFK and STAT3 signaling, as well as tumorigenicity in human breast cancer cells in vitro and in vivo." (PMID 36077422, 2022). "Combined with chip-seq data acquired from Cistrome Data Browser and molecular experiments, we proved that NRF1 is the accurate TF for PTPN2 in breast cancer cell lines." (PMID 36341348, 2022). "CD8+ T cells with metastatic PTPN2 defect saliently inhibits the formation of mammary tumor in mice." (PMID 35461336, 2022). "Among these results, cytosine located in gene PTPN2 (chromosome 18: 12789928), which is a tumor suppressor gene with a low expression ratio in breast cancer, was a putative site regulated by NSUN2 and YBX1." (PMID 35456483, 2022). "Considering the YBX1 can stabilize mRNA, the impaired recognition by YBX1 will lead to the decay of PTPN2 and contribute to the development of breast cancer." (PMID 35456483, 2022). "One study provided a possible mechanism for PTPN2 in breast cancer expressing epidermal growth factor receptors (EGFRs) and ER." (PMID 34884670, 2021). "PTPN2 was also found to be associated with activation of PI3K/AKT pathway and tamoxifen resistance in breast cancer." (PMID 32207560, 2020). "Another study found that PTPN2 deficient T cells were more efficient in restraining AT3-OVA mammary carcinoma cells, but the PTPN2–/– OT-1 CD8 T cells expressed lower frequencies of PD-1+ or LAG-3+ cells." (PMID 33425916, 2020). "Few studies have explored the role of PTPN2 in breast cancer; therefore, we aimed to evaluate the clinical value of PTPN2 in a large breast cancer cohort." (PMID 30515568, 2019). "PTPN2 was knocked down in three cell lines, representing different breast cancer subtypes, with siRNA transfection." (PMID 31025094, 2019). "While PTPN2 is commonly found deleted in non-Hodgkin lymphoma and T-cell acute lymphoblastic leukaemia, few studies exist on the role of PTPN2 in breast cancer." (PMID 31025094, 2019). "We have previously shown that PTPN2 can predict tamoxifen therapy benefit in post-menopausal breast cancer patients." (PMID 31025094, 2019). "We previously found a correlation between PTPN2 gene deletion and high levels of phosphorylated Akt in breast cancer patients." (PMID 30515568, 2019). "We confirm previous studies showing that the PTPN2 protein is lost in half of the breast cancer cases and gene deletion occurs in 15–18% of the cases." (PMID 31025094, 2019). "Various substrates of PTPN2 play important roles in the genesis and progression of breast cancer amongst others the epidermal growth factor receptor (EGFR), STAT3, and proposedly the Met receptor." (PMID 31025094, 2019). "Protein expression and gene copy number of PTPN2 were analysed in a cohort of pre-menopausal breast cancer patients with immunohistochemistry and droplet digital PCR, respectively." (PMID 31025094, 2019). "Three breast cancer cell lines were transfected for 48 h with siRNA targeting PTPN2 or with scrambled siRNA." (PMID 31025094, 2019). "In this study, the role of PTPN2 was explored in the different subtypes of breast cancer in both a subset of pre-menopausal breast cancer patients and cell lines." (PMID 31025094, 2019). "Another study demonstrated that PTPN2 was absent in a large proportion of “triple-negative” primary human breast cancers and PTPN2 overexpression would suppress tumor growth." (PMID 28400551, 2017). "However, most PTPN family members function as tumor suppressors in breast cancer, including PTPN2, PTPN4, PTPN6, PTPN9, PTPN13, PTPN14, and PTPN23." (PMID 35957898, 2022).
breast cancer (continued). "The biological functions of PTPN2 vary according to breast cancer subtypes." (PMID 36077422, 2022). "PTPN2-deficient T cells noticeably repressed tumor formation in mice, and KO of PTPN2 in HER2 CAR-T cells enhanced tumor eradication in a preclinical model with HER2 positive mammary tumors." (PMID 34830003, 2021). "Importantly, we found that Ptpn2 deletion led to the effective eradication of HER‐2‐E0771 mammary tumours and this was accompanied by the increased infiltration of mCherry+ HER‐2 CAR T cells into HER‐2‐E0771 mammary tumours in vivo." (PMID 31803974, 2020). "The inducible overexpression of PTPN2 not only repressed IFNγ‐induced p‐STAT‐1 and Cxcl9/10 expression, but most importantly also the recruitment of PTPN2‐deficient CAR T cells to HER‐2‐E0771 mammary tumours in vivo." (PMID 31803974, 2020). "PTPN2‐deficient CAR T cells markedly suppressed tumour growth, even when the tumours were allowed to grow to one quarter (50 mm2) of the maximal ethically permissible mammary tumour burden prior to CAR T‐cell therapy." (PMID 31803974, 2020). "Finally, four genes (PTPN2, MTSS1, EPN3, and C17ORF37) are associated with cell migration and adhesion and/or poor prognosis of breast cancer." (PMID 21339811, 2011). "Thus, the biological function of PTPN2 in breast cancer is a double-edged sword." (PMID 36077422, 2022). "The PTPN2 protein has been shown to be lost in ER-negative breast cancer, more so in triple-negative breast cancers (TNBC) and we have previously found that the protein is expressed at low levels in 53.3% of the tumours in a cohort of low-risk breast cancer patients." (PMID 31025094, 2019). "Furthermore, the results suggest that the role of PTPN2 is subtype-related and should be further investigated to assess how this could affect breast cancer prognosis and treatment response." (PMID 31025094, 2019). "None of the breast cancer subtypes showed a direct correlation with PTPN2 staining or copy loss." (PMID 31025094, 2019). "Moreover, in an adoptive transfer setting, Ptpn2-deficient T cells inhibit tumor growth, and in CAR-T cells a lack or inhibition of PTPN2 fosters the production, antigen-specific activation, and cytotoxicity of CD8+ HER2 CAR-T cells ex vivo, while reducing HER2+ E0771 mammary tumor growth." (PMID 38022587, 2023). "To further assess the therapeutic potential of targeting PTP1B and PTPN2 in cancer with small molecule inhibitors, we employed two additional syngeneic tumor models, MC38 colon and AT3 mammary tumor models." (PMID 37500611, 2023). "SHP-1, PTP1b, PTPN2, and PTPRD are all phosphatases that influence the JAK-STAT pathway in gastric and breast cancer." (PMID 34884670, 2021). "Our own studies indicate that the deletion of PTPN2 in CAR T cells drives the expression of CXCR3 and the trafficking of CAR T cells to CXCL9/10‐expressing mammary tumours." (PMID 31803974, 2020). "Similarly, deletion of PTPN2 enhanced the efficacy of HER2-specific mouse CAR-T cells, resulting in superior clearance of HER2-expressing E0771 mammary tumours in vivo and prolonged survival." (PMID 38334623, 2024). "The deletion of PTPN2 in syngeneic tumors in mice, including xenografted B16F10A melanomas and MC38 colorectal adenocarcinomas, as well as orthotopic AT3 mammary tumors, can enhance T cell mediated anti-tumor immunity and the response to PD-1 checkpoint blockade." (PMID 37500611, 2023). "Ptpn2 knockdown enhanced the tumour antigen‐specific activation/cytotoxic potential and killing capacity of HER‐2 CAR T cells ex vivo (Fig EV5C–E) and markedly repressed the growth of HER‐2‐E0771 mammary tumours in vivo." (PMID 31803974, 2020). "As PTPN2 is not frequently studied in breast cancer, we aimed to explore the role of PTPN2 and the effects of its loss in breast cancer." (PMID 31025094, 2019).
breast cancer (continued). "We enumerated the positive or negative modulatory effects of PTPN2 in a variety of cancers, including intestinal cancers, breast cancer, glioma, hepatocellular carcinoma, skin cancer, lung cancer, ovarian cancer, laryngeal cancer, thyroid cancer, and B-cell lymphoma." (PMID 36077422, 2022). "Protein tyrosine phosphatase non-receptor type 2 (PTPN2), also known as T-cell PTP, is another tyrosine-specific PTP that may modulate ER+ breast cancer sensitivity to tamoxifen treatment by lowering the JAK-STAT cancerous signaling pathway." (PMID 34884670, 2021).
rheumatoid arthritis (29 papers, 2011 to 2025). A chronic, systemic autoimmune disorder characterized by inflammation in the synovial membranes and articular surfaces. "Previous studies demonstrated that several variants located in PTPN2 were significantly associated with inflammatory bowel disease, celiac disease, rheumatoid arthritis 34 and diabetes." (PMID 32207560, 2020). "Another gene–gene interaction of importance is between HLA-DRB1 and PTPN2, which are both key susceptibility genes in anti-CCP–positive rheumatoid arthritis (anti-CCP + RA)." (PMID 41026325, 2025). "Particularly, variants within the gene locus encoding protein tyrosine phosphatase non-receptor type 2 (PTPN2) are strongly associated with increased risk for developing IBD, but also many other autoimmune/inflammatory diseases such as rheumatoid arthritis (RA) or type I diabetes (T1D)." (PMID 33466682, 2021). "A study of rheumatoid arthritis single-cell RNA sequencing data demonstrated that five genes, KLRG1, CRTAM, SLAMF7, PTPN2, and KLRD1, were downregulated in activated and effector T cells isolated from synovial fluids." (PMID 38254179, 2024). "Loss-of-function variants of protein tyrosine phosphatase non-receptor type 2 (PTPN2) enhance risk of inflammatory bowel disease and rheumatoid arthritis; however, whether the association between PTPN2 and autoimmune arthritis depends on gut inflammation is unknown." (PMID 33055428, 2020). "We previously discovered that single nucleotide polymorphisms (SNPs) in PTPN2/22 (T-cell negative-regulators) occur in 78% of rheumatoid arthritis (RA), along with Mycobacterium avium paratuberculosis (MAP) infection in 33% of patients." (PMID 31817071, 2019). "Recently, it has been reported that the single nucleotide polymorphisms (SNPs) of STAT4, PTPN2, PSORS1C1, and TRAF3IP2RA genes are associated with the clinical efficacy of tumor necrosis factor (TNF) inhibitors in the treatment of rheumatoid arthritis (RA) patients." (PMID 31709198, 2019).
Crohn disease (28 papers, 2010 to 2025). A gastrointestinal disorder characterized by chronic inflammation involving all layers of the intestinal wall, noncaseating granulomas affecting the intestinal wall and regional lymph nodes, and transmural fibrosis. "Seven shared risk genes (CD40, PTPN22, CD226, BATF, PRKCB, RasGRP1, and PTPN2) are involved in cytokine pathways linked to Crohn’s disease." (PMID 40839671, 2025). "It has also been discovered that the Crohn's disease-associated PTPN2 variation (rs2542151) increases mTOR activity, which impairs autophagy." (PMID 39883213, 2024). "rs12955302 is located in an intron of PTPN2, an immunologically salient gene, and is associated with a range of IMDs including Crohn's disease, ulcerative colitis, T1D, and coeliac disease." (PMID 39241920, 2024). "A recent meta-analysis corroborated the link between PTPN2 variants and inflammatory bowel diseases, notably Crohn disease (CD)." (PMID 36755664, 2022). "Notable genes with VDR binding included PTPN2 associated with Crohn’s disease and T1D, and IRF8, which was associated with MS45." (PMID 28377587, 2017). "The PTPN2 gene mutation in T1D patients play a direct role in the destruction of beta cells while in Crohn's disease patients, it modulates the innate immune responses." (PMID 26734582, 2015). "The PTPN2 gene mutation in T1D patients plays a direct role in the destruction of beta cells, while in Crohn's disease patients, it modulates the innate immune responses." (PMID 26734582, 2015). "In Crohn's disease, SNP variation in the PTPN2 gene influences susceptibility to the disease and mechanism of pathogenesis." (PMID 26734582, 2015). "A SNP mutation (rs2542151-G) in the PTPN2 gene is found not only in T1D, but in Crohn's disease as well." (PMID 26734582, 2015). "Not only were a distinct set of iron handling proteins altered by the disease severity, but the overall directionality of the effects was the opposite of those altered by the PTPN2 variant, with iron regulatory proteins largely increased in Crohn’s disease patients." (PMID 40244226, 2025). "It indicates that PTPN2 gene variants and SNP rs7234029 have a crucial role in Crohn’s disease." (PMID 35163260, 2022). "The mutation in PTPN2 could not only cause Crohn's disease but also T1D due to the presence of this mutation in both disease states." (PMID 26734582, 2015). "GWAS have showed that PTPN2 is a T1D susceptibility gene and risk locus for Crohn's disease." (PMID 26734582, 2015). "The presence of Crohn's disease-associated ATG16L1 (T300A) inhibits TNF and IFN-γ-induced PTPN2 protein increase." (PMID 39883213, 2024). "As previously stated, there is an aberrant T cell differentiation and intestinal dysbiosis in Crohn's disease, which PTPN2 seems to play a role in." (PMID 26734582, 2015). "Serum proteomic analyses revealed that the “iron homeostasis signaling pathway” was the main pathway downregulated in Crohn’s disease (CD) patients carrying the PTPN2 risk allele, independent of disease activity." (PMID 40244226, 2025). "PTPN2 expression plays an important role in regulating signal transduction and it is of pivotal importance to the pathogenesis of many diseases such as T1D and Crohn's disease." (PMID 26734582, 2015). "However, the exact role of PTPN2 in Crohn's disease (CD) and ulcerative colitis (UC) and its phenotypic effect are unclear." (PMID 22457781, 2012). "Notably, PTPN2 appears to modulate the gut microbiome and loss of PTPN2 is associated with enhanced CEACAM expression and enhanced AIEC uptake and intracellular survival, suggesting that Crohn’s disease may reflect the interplay of pathogenic E. coli and distinctly susceptible hosts." (PMID 36865539, 2023). "A possible suggestion for future studies is to perform a large-scale GWAS investigation to estimate the incidence of SNP's in PTPN2 and PTPN22 in patients diagnosed with both T1D and Crohn's disease." (PMID 26734582, 2015).
Crohn disease (continued). "The protein tyrosine phosphatase genes, PTPN2 and PTPN22, are of vital importance to both T1D and Crohn's disease." (PMID 26734582, 2015). "Susceptibility loci related to intestinal macrophage functions have been unraveled in Crohn’s disease patients, including NOD2, ATG16L1, CX3CR1, IL12p40, IL23R, JAK2, STAT3, and protein tyrosine phosphatase non-receptor type 2 (PTPN2)." (PMID 39095853, 2024). "This review article is focused on the impact of SNP's in PTPN2 (protein tyrosine phosphatase, non-receptor type 2) and PTPN22 (protein tyrosine phosphatase non-receptor type 22) on the development of Crohn's disease and T1D." (PMID 26734582, 2015).